EEF1A1P26 (eukaryotic translation elongation factor 1 alpha 1 pseudogene 26)
Gene: Processed pseudogene on chromosome 7 (14,190,795 to 14,192,157, forward strand). Ensembl gene ENSG00000233167.
Diseases named in the same sentence as EEF1A1P26 in open-access papers:
EEF1A1P26 is named in the same sentence as 1 disease in open-access papers, as found by Europe PMC text mining. Sharing a sentence is not in itself a finding about the gene and the disease.
cancer (1 paper, 2023). A tumor composed of atypical neoplastic, often pleomorphic cells that invade other tissues.